CD4 (CD4 molecule)
Diseases named in the same sentence as CD4 in open-access papers (continued):
Sharing a sentence is not in itself a finding about the gene and the disease.
AIDS (continued). "For example, one Fellow's work resulted in an increase in the volume of CD4 tests [a test of the immune function, used for HIV/AIDS care] performed by the Partner Organization, from 100 to 300 a day, while simultaneously increasing test quality and reliability." (PMID 17335578, 2007). "SP-D levels were significantly higher in AIDS patients (median 577.79 ng/ml) compared to normal subjects (median 406.72 ng/ml; Kruskall Wallis p = 0.03) or HIV-infected individuals with CD4 count greater than 200 cells/μl (median 382.60 ng/ml; Kruskall Wallis p = 0.05)." (PMID 17567900, 2007). "In spite of several studies over the last twenty years, the relative value of the CD4 percentage and CD4 absolute count in predicting the onset of AIDS-related events is not settled." (PMID 16916461, 2006). "The higher fitness of CRF02_AG was evident for isolates from patients with CD4+ T cell counts >200 cells/μL (non-AIDS) or CD4+ T cell counts <200 cells/μL (AIDS), and was independent of the co-receptor tropism." (PMID 16817969, 2006). "Since the management of AIDS is dependent on CD4 enumeration, we do not advocate the use of the absolute lymphocyte count as a predictor of AIDS-related events." (PMID 16916461, 2006). "This cross-sectional population study in Uganda included 20 HIV infected persons with no symptoms of AIDS and a CD4 count above 200 mill./liter." (PMID 15167940, 2004). "Moreover, PLH with AHD have poorer HRQoL than PLH without AIDS or with higher CD4 counts, particularly in the dimensions of physical and mental health." (PMID 40369301, 2025). "Furthermore, a lower CD4/CD8 ratio was observed in the treatment naïve PWHPROG compared to PWHEC and PWHART, suggesting immune activation and an increased likelihood of developing non-AIDs-related comorbidities." (PMID 40936922, 2025). "Notably, 15–30% of individuals undergoing ART achieve viral suppression but fail to restore adequate CD4+ T cell counts, being defined as immunological non-responders (INR) and remaining at increased risk of disease progression to AIDS." (PMID 40733502, 2025). "In AIDS, the absence of CD4 immunity results in exuberant and often fatal PJP." (PMID 39745390, 2025). "Similar observations have been made in patients with HIV/AIDS as antiretroviral therapy leads to the reestablishment of a competent immune system and anti-CMV therapy with ganciclovir can be discontinued as soon as the CD4 count is maintained above 100 cells/mm371." (PMID 40676060, 2025). "At the same time, the increasing number of CD8+ T lymphocytes exerts partial control of the infection, although insufficient to prevent (in the absence of therapy) the slow and progressive depletion of CD4+ T lymphocytes and the eventual progression to acquired immunodeficiency syndrome (AIDS)." (PMID 41415703, 2025). "When a patient with AIDS combined with PTB presents to the clinician, the clinician should evaluate the patient for the presence of extrapulmonary tuberculosis, pulmonary cavitation, and other pulmonary infectious diseases, as well as having a test for the patient’s CD4+ T-cell counts and CAR." (PMID 40510348, 2025). "Additionally, they often started ART with a higher CD4 cell count and a VL ≤100.000 copies/mL and without a previous AIDS diagnosis." (PMID 39710424, 2025). "The HIV-induced destruction of CD4+ T cells, whether directly or indirectly, leads to the loss of both HIV-specific and non-specific immune responses during the AIDS stage." (PMID 40566275, 2025). "Notably, a persistently low CD4+/CD8+ ratio (e.g., <0.4–0.5) during ART is associated with an elevated risk of non-AIDS morbidity and mortality, independent of absolute CD4+ counts." (PMID 40868140, 2025). "In line with the claim that aberrant CD4+ T cell homeostasis is a major feature of HIV infection, these results indicate that the CD4+ T cell population, rather than the CD8+ T cell population, plays the key role in HIV/AIDS immune impairment, in association with the elevated PD1 levels." (PMID 40733503, 2025).
AIDS (continued). "According to the definition endorsed by the European Centre for Disease Prevention and Control (ECDC) and the World Health Organization (WHO), late diagnosis, rather than late presentation, is defined as having a CD4 count <350 cells/μl or an AIDS-defining event." (PMID 40469732, 2025). "However, statistical significance was not confirmed in multivariate analysis [AIDS: adjusted HR (aHR) 0.48, 95% CI 0.20–1.16, p = 0.103; CD4 > 500 cells/mmc: aHR 1.58, 95% CI 0.84–2.97, p = 0.155)." (PMID 39857082, 2025). "Using the Cost-Effectiveness of Preventing AIDS Complications-International model, we simulated a cohort of non-hospitalised people living with HIV (aged >19 years) initiating antiretroviral therapy (ART), 25% of whom had AHD (CD4 count <200 cells per μL and/or WHO stage 3 or 4 disease)." (PMID 40712615, 2025). "Furthermore, some clinical indicators such as WBC, PLT, TC, TG, and ALT could predict the CD4+ count, CD8+ count, CD4/CD8 ratio levels and recuperation of HIV/AIDS patients, therefore, should be monitored by clinicians." (PMID 39742334, 2024). "In Western Europe, 45–50% of newly diagnosed people with HIV (PWH) are identified and enter care late, i.e. with a CD4+ T-cell count < 350 cells/μL or with an AIDS-defining event regardless of the CD4+ T-cell count, with only 89% of PWH being aware of their HIV status." (PMID 39611208, 2024). "PLHIV with an AIDS event had lower CD4 counts at ART initiation compared to those without an AIDS event (median 178 cells/μL, IQR 73–313 vs. median 280 cells/μL, IQR 144–433), while the VLs were comparable (median 24,930 copies/mL, IQR 350–164,313 vs. median 10,000 copies/mL, IQR 219–110,000)." (PMID 38381307, 2024). "However, beta diversity, or bacterial composition, has not shown consistent patterns aside from CD4+ T cell depletion when compared to PLWH without AIDS." (PMID 39597610, 2024). "Indeed, CD4-negative epidermal keratinocytes from co-infected AIDS patients without genital HSV-mediated lesions were observed to be infected by HIV-1, possibly pseudotyped with HSV Env." (PMID 38787201, 2024). "Compared with immune responders (IRs) who have restored their CD4 T cell numbers and functions, CD4 T cells from these INRs exhibit prominent mitochondrial dysfunction and premature aging, which play a major role in increasing the incidence of non-AIDS, non-communicable diseases (NCDs)." (PMID 38895099, 2024). "Second, individuals without AIDS diagnosis or CD4 count record within three months of initial HIV diagnosis were excluded from the analysis because of the uncertainty about whether they are LPAD or not." (PMID 38896338, 2024). "B2M could serve as an independent indicator for predicting the advancement of AIDS, irrespective of the CD4 + T cell count." (PMID 38743119, 2024). "Also, note the low CD4 count and high HIV RNA count are suggestive of AIDS." (PMID 39104976, 2024). "The present study estimated the prevalence of cryptococcal antigenemia by LFA in 230 consecutive adult patients with AIDS and CD4+ count ≤ 200 cells/mm3 without previous diagnosis of cryptococcosis, analyzed its accuracy parameters, and compared its sensitivity with that of other diagnostic tests." (PMID 39057375, 2024). "Therefore, routine registration of CD8 count and CD4/CD8 could help to assess immune recovery and to predict non‐AIDS complications and mortality in the long‐term." (PMID 38494667, 2024). "Also, individuals with a history of being significantly immunocompromised, such as those with CD4 T cell counts less than 200 and/or history of AIDS were excluded, and we do not know how these vaccine regimens would perform in such a population." (PMID 38782902, 2024). "Levels of CD3+, CD4+, CD4+/CD8+, B cells, and NK cells were lower in the observation group (P<0.05), were significantly lower in asymptomatic patients compared with patients in the acute phase (P<0.05), and were significantly lower in patients with AIDS than those in asymptomatic patients (P<0.05)." (PMID 39554636, 2024).
AIDS (continued). "However, despite the considerable advances achieved in the field, PLWH are often diagnosed at a late disease stage, defined as having a CD4+ T-cell count less than 350 cells/μL or presenting with an AIDS-defining event, regardless of the CD4+ T-cell count." (PMID 38525766, 2024). "This might also be true for persons living with HIV, as not all individuals progress to AIDS when reaching a set number of circulating CD4+ T-cells." (PMID 36813761, 2023). "CMVR was more prevalent in AIDS patients with the following characteristics: white and non-Hispanic (60%, 95%CI 55%-64%, I2 = 95%), homosexual (70%, 95%CI 67%-74%, I2 = 93%), HIV RNA load ≥ 400 copies/mL (82%, 95%CI 70%-91%, I2 = 96%), or CD4+ T-cells <50 cells/μL (78%, 95%CI 71%-85%, I2 = 86%)." (PMID 37305416, 2023). "In this respect, a third dose of a mRNA vaccine following the primary cycle has been shown to strongly boost humoral albeit not T-cell responses in PLWH with advanced disease at the time of HIV diagnosis (CD4 + T-cells < 200/μL and/or AIDS), irrespective of the current CD4 + T-cell count [102••]." (PMID 36680700, 2023). "Furthermore, resistance to AIDS in natural hosts of SIV is independent of CD4+ T-cells counts and/or their swift and robust restoration in blood and tissues." (PMID 36813761, 2023). "Persistent low CD4+ T cell levels in these patients lead to an increased incidence of AIDS and non-AIDS events, such as metabolic syndrome, cardiovascular disease, liver disease, neurocognitive impairment, and malignant tumors, which in turn increase the risk of mortality." (PMID 37205108, 2023). "In addition, it is possible that the CD4/CD8 ratio and CD8 count are linked to some, but not all, types of non-AIDS events." (PMID 37639938, 2023). "Notably, variables such as the patient’s sex, zidovudine treatment, low CD4 cell count, high viral load, and lower body mass index may contribute to a higher likelihood of anemia in HIV/AIDS patients." (PMID 38085717, 2023). "Relatedly, some HIV-related factors that may have influenced the findings were not considered due to the limited sample size, and future analyses should examine the impact of HIV duration, viral load, AIDS, antiretroviral therapy (ART), duration on ART, CD4 nadir, and CD4 t-cell count." (PMID 37265553, 2023). "In the past, the guidelines for starting appropriate treatment were an initial CD4 cell count < 350 cells/mm3 and HIV RNA count > 55,000 copies/mL; this criterion was calculated by estimating the point in time when the probability of developing AIDS within 3 years is ≥ 30%21." (PMID 37016006, 2023). "Tixagevimab/cilgavimab at a dose of 150/150 mg is recommended for individuals with advanced or untreated HIV infection, defined as having CD4 counts < 200 cells/mm3 or a history of an AIDS-defining condition without immune reconstitution or clinical manifestations of symptomatic HIV." (PMID 36851791, 2023). "The CD4+ T cell numbers were further determined for 155 HIV- positive samples, following which the cases were classified into different clinical stages: the primary infection stage (15 cases, 9.7%), the middle stage of infection (63 cases, 40.6%), and AIDS stage (77 cases, 49.7%)." (PMID 38314093, 2023). "Those excluded due to lack of baseline measurements (n = 1608) were more likely to be female (12.6% vs. 8.1%), non-MSM (36.2% vs. 32.3%), non-white (7.2% vs. 6.5%), with clinical AIDS (8.8% vs. 7.1%), and with lower median CD4 cell count (306 vs. 325 cells/μL) at baseline." (PMID 36016299, 2022). "Low CD4 counts, unsuppressed viral load, poor adherence, and drug resistance could be used as predictors for increased mortality to monitor the quality of HAART and improve clinical management of HIV/AIDS patients." (PMID 36467882, 2022). "However, most of the current clinical guidelines for adults living with HIV AIDS recommend starting ART regardless of CD4 T-cell count." (PMID 35359787, 2022).
AIDS (continued). "It cannot be excluded that some of the excluded cases presenting with less than 200 cells/mm3 CD4+ T cell counts at the time HIV diagnosis, or cases who succumbed of AIDS-related complications within 1 year of diagnosis of HIV, may have become infected with HIV within 130 days." (PMID 35732657, 2022). "The CDC HIV/AIDS Surveillance Project, including 304 homeless across 19 sites throughout the United States demonstrated that PLWHA experiencing homelessness had lower adherence to antiretroviral treatment, lower CD4 cell count, lower likelihood of viral suppression." (PMID 35144557, 2022). "However, we did not observe the difference between DTG and EFV in treatment discontinuation, which was similar to another study that included patients initiating DTG or non-DTG with CD4 < 350 cells/μL or with AIDS-defining events." (PMID 36700216, 2022). "For the CD4+ lymphocytes >500 cells/μL endpoint, the variables that remained statistically significant throughout the analysis were: (i) no history of AIDS at baseline (HR: 5.28 (IQR: 1.91–14.63), p = 0.001) and (ii) a viral load <5 log copies/mL (HR: 2.13 (IQR: 1.26–3.59), p = 0.004;." (PMID 35407496, 2022). "Most cryptococcal infections occur among individuals having less than 200 CD4+ T cells/μL, and a CD4+ T cell count of ≤ 100 cells/μL is recommended as the routine criterion by the World Health Organization for screening cryptococcal infection of HIV/AIDS patients." (PMID 35130846, 2022). "Furthermore, the CD4+ T-cell count recovery speed of RI, LI non-AIDS and LI AIDS patients were 16, 11 and 11 cells/mm3 per month, respectively whereas the corresponding CD4/CD8 ratio recovery speed was 0.042, 0.028 and 0.018 per month, respectively." (PMID 36483196, 2022). "We also could not classify as late or non-late presenters those who did not have CD4 count or AIDS events available before starting treatment, although they accounted for only 3% of the entire cohort." (PMID 35428209, 2022). "None of the lesions described is exclusive to HIV/AIDS patients; however, all of them present higher prevalence, severity, and progression in comparison to HIV-negative patients, especially in low CD4+ T lymphocyte counts and, in some cases, associated with the use of ART." (PMID 36143891, 2022). "In addition, HIV/AIDS patients at II (BII = −105.74,95% CI:−139.09, −72.40, P < 0.001), III (BIII = −215.59, 95% CI:−246.81, −184.36, P < 0.001), and IV (BIV = −254.53, 95% CI−298.82, −210.24, P < 0.001) clinical stages experienced a lower CD4 cell count." (PMID 35846073, 2022). "The European Late Presenter Consensus working group defines the late presentation of HIV as a lymphocyte CD4+ count lower than 350 cells/μL at the time of diagnosis or, regardless of the lymphocyte count, presentation with an AIDS-defining event at the time of diagnosis." (PMID 35457436, 2022). "Therefore, it seems that different levels of CD4+ T-cell count do not necessarily require a different timing of ART initiation for AIDS/PCP patients with varying CD4+ T-cell counts." (PMID 36008855, 2022). "Conversely, immunocompromised individuals lacking a necessary component of the immune system, namely CD4+ T cells as seen with HIV/AIDS, generally fail to control the initial infection or maintain the integrity of the lung granulomas containing latent cryptococcal cells leading to host pathology." (PMID 35615354, 2022). "We used extended Cox proportional hazard models to estimate the hazard ratios (HRs) for the association between CD4/CD8 ratio over time and a composite endpoint of the occurrence of the first AIDS event, first serious non-AIDS event or overall mortality occurring from 6 months after enrolment." (PMID 35428209, 2022). "Regarding clinical variables, prevalence of very good or good self-rated health was lower among those ever diagnosed of AIDS (53.9%), patients with viral load more than 200 copies (33.8%) or low CD4 count (20.9%), with comorbidities (33.0%) and not receiving ART (44.4%)." (PMID 33516173, 2021).
AIDS (continued). "Furthermore, the study conducted in Calgary, Canada reported that a low CD4 cell count, presence of an AIDS defining illness and no current use of ART were strongly correlated with hospitalization (p <0.01)." (PMID 33882077, 2021). "Furthermore, they showed that HIV-infected patients in advanced disease stages (less than 200 CD4+ T cells/μl) and especially those with AIDS symptoms had higher M-MDSC levels than those without AIDS symptoms." (PMID 34753323, 2021). "Moreover, the patient did not progress to developing AIDS during a 6-month observation period, despite an extremely low CD4 cell count of 45/μL." (PMID 34072078, 2021). "A 61-year-old male with HIV/AIDS who was not on antiretroviral therapy and had advanced immunosuppression with a CD4+ T-lymphocyte count of 3 cells/μL sought medical attention for multiple somatic issues including subjective fevers, shortness of breath, and intermittent chest pain." (PMID 34941094, 2021). "Some long-term non-progressors (LTNPs) have decreasing CD4+ T cell counts and progress to AIDS." (PMID 34082709, 2021). "Our previous study showed that newly diagnosed male AIDS patients had decreased total cholesterol (TC) levels, uric acid (UA) levels and high-density lipoprotein cholesterol (HDL-c) levels as well as increased triglyceride (TG) levels, especially patients with CD4+ counts < 200/μL." (PMID 34794501, 2021). "As such, some individuals (e.g., diagnosed with an advanced AIDS-defining event that never received treatment or with a high CD4 without the need for immediate treatment) may not be registered in SALVAR." (PMID 34774077, 2021). "Thus, the CD4+ T-cell count records of patients with HIV/AIDS were often not available for every year." (PMID 34326884, 2021). "The CD4 level of the present case was lower than normal, but not too low which could be due to AIDS medication." (PMID 33681092, 2021). "Regardless of the CD4 cell counts and whether ARTs have been administered, none of the patients progressed to the severe form or to death, despite some of the AIDS patients presenting with baseline lung injury stimulated by HIV." (PMID 34646783, 2021). "The sole use of routine HIV markers like CD4 count and viral RNA load, may not accurately reflect the impact of multisystem injury in AIDS, specifically in terms of neurocognitive disorders." (PMID 34348754, 2021). "Thus, 784,000 persons were living with HIV in China in 2019, of whom 60% were not receiving ART and 165,018 had AIDS (CD4 <200)." (PMID 32818410, 2020). "In our study the vast majority were classified as LP based on their CD4 cell count rather than an AIDS-event, which may indicate a need to increase testing based on indicator diseases as well as among individuals belonging to high prevalence populations." (PMID 33028235, 2020). "In the older group, independent predictors of death included: being urban residents, nadir CD4+ T-cell counts <200 cells/μL, not being on cART, and having comorbidities such as Pneumocystis pneumonia, hepatitis C, talaromycosis, non-AIDS malignancy, and kidney disease." (PMID 33681235, 2020). "Furthermore, several studies have also shown that incomplete recovery of CD4 counts, CD8 counts, or CD4/CD8 ratio is independently associated with a higher risk of severe outcomes, such as AIDS- or non-AIDS-related events and death." (PMID 33131455, 2020). "Among acquired immunodeficiency syndrome (AIDS) patients, long-term non-progressor (LTNP) is a special kind of being that can maintain high CD4+ T-cell counts and control HIV replication for years." (PMID 32357558, 2020). "The self-regulatory immune system responds by attempting to restore the CD4+ count, but little is known about the complexity around the corresponding adaptation on the optimal set points of the many clinical attributes stored as EHR in the HIV/AIDS prospective cohort studies." (PMID 32190387, 2020).